IL6 (interleukin 6)
Diseases named in the same sentence as IL6 in open-access papers (continued):
Sharing a sentence is not in itself a finding about the gene and the disease.
Obesity (continued). "Other circulating factors released in obesity, such as IL-6 and TNF-α, further increase BBB permeability." (PMID 37086380, 2023). "In a randomized, double-blind, placebo-controlled clinical study, the multi-strain probiotic Ecologic® Barrier influenced TNF-α and IL-6 in a dose-dependent manner in postmenopausal women with obesity." (PMID 37371961, 2023). "In rodents, the anti-obesity effect of IL-6 is partially exerted at the level of the brain, perhaps in the hypothalamus and hindbrain [139,]." (PMID 37268247, 2023). "Supplementation with vitamin D3 decreased the production of proinflammatory cytokines: TNFα, PAI-1 (plasminogen activator inhibitor-1), IL-6, and ROS and pro-fibrotic genes in studies on AT biopsies from patients with obesity and 25(OH)D insufficiency." (PMID 38276294, 2023). "Further IL-6 levels showed positive correlation with BMI and thus it appears that IL-6 can function as a substitute marker for obesity." (PMID 37992066, 2023). "Increased circulating pro-inflammatory cytokines and adipokines (e.g. TNF-α, leptin, resistin, plasminogen activator inhibitor-1, CRP, IL-1β and IL-6) contribute to systemic inflammation in obesity but are also established predictors of cognitive impairment." (PMID 37086380, 2023). "Obesity is characterized by chronic low-grade inflammation with a moderate increase in circulating levels of IL-6, which can contribute to a rise in IL-6 and impairs sleep quality." (PMID 37489445, 2023). "On the other hand, this transcription factor has been found to regulate the expression of obesity-related bioactive molecules (i.e., IL-6, IGF-1, and leptin), further suggesting the potential role of CEBP-β in mediating BC cell/adipocyte crosstalk." (PMID 37447165, 2023). "In the mammary adipose tissue of humans and mice with obesity, IL-6 can be secreted by macrophages with a proinflammatory phenotype in an NADPH oxidase 2-dependent manner." (PMID 36593475, 2023). "Differences between the overweight, obese and severe obesity groups were observed for IL-1β, IL-6, and IL-10." (PMID 37336969, 2023). "Obesity is a chronic, mild inflammatory state associated with increased levels of inflammatory biomarkers, such as tumor necrosis factor‐α (TNF‐α), interleukin 6 (IL‐6), and C‐reactive protein." (PMID 37904706, 2023). "Proinflammatory cytokines TNFα, IL-1β, and IL-6, are produced by macrophages and adipocytes, the primary cells involved in obesity and metabolic disorders." (PMID 36830566, 2023). "One proposed mechanism underlying the link between obesity, inflammation, and CRC risk is through the secretion of inflammatory cytokines such as TNF-α, IL-1β, IL-6, and monocyte chemoattractant protein (MCP)-1 by adipose tissue-derived cells." (PMID 36839339, 2023). "For instance, circulating levels of chemerin strongly correlated with markers of inflammation, such as TNF-α, IL-6, and C-reactive protein, in the context of obesity." (PMID 36883565, 2023). "Another study observed a significant reduction in C‐reactive protein (CRP) and Interleukin‐6 (IL‐6) levels with vitamin C supplementation in patients with obesity, hypertension, and/or diabetes." (PMID 37823170, 2023). "Elevated levels of IL-6, an endogenous pro-inflammatory cytokine for neutrophils, correlate with increased neutrophil counts in cases of obesity-related asthma." (PMID 37834850, 2023). "Experimental evidence show that IL-6 produced by adipocytes is deleterious, while myeloid and muscle cells production of IL-6 is protective in obesity, possibly explaining the discrepancy between its inflammatory nature and metabolic importance." (PMID 36994095, 2023). "In particular, we found a significantly abnormal expression of IL-6 in astrocytes after obesity-related circRNA depletion under obesity-related in vitro conditions." (PMID 37047207, 2023).
Obesity (continued). "It has also been indicated that endothelial cells from subjects with obesity tend to disrupt adipocyte function through the inflammatory signaling of IL-6 and IL-1β when co-cultured in vitro." (PMID 36766750, 2023). "The increase in the IL-6 level induced by obesity decreases insulin sensitivity in the liver, muscles, pancreas, and white adipose tissue (WAT)." (PMID 37371961, 2023). "Large-scale GWAS of T2DM and breast cancer have provided evidence for shared susceptibility genes, including a fat mass and obesity-associated gene (FTO), the interleukin-6 (IL-6) gene, and heat-shock protein 60 encoded by HSPD1 gene." (PMID 37510134, 2023). "The subacute inflammatory state associated with obesity is believed to be induced and sustained by pro-inflammatory and anti-inflammatory cytokines, such as TNF-α, IL-6, and resistin." (PMID 37241120, 2023). "Obesity is characterized by mild chronic inflammation, which leads to the release of proinflammatory cytokines such as interleukin-6 and tumor necrosis factor-α." (PMID 37397759, 2023). "Obesity is associated with a pro-inflammatory state with adipocytes releasing and signaling the release of many pro-inflammatory cytokines such as CRP and IL-6." (PMID 37836549, 2023). "Patients in the PLEX group were mean aged 47 years old, 85% males, with obesity (80%) as most prevalent comorbidity; and significantly higher ferritin, IL-6 and lower platelet count, as compared to control group." (PMID 36599875, 2023). "Obesity is regarded as a kind of chronic inflammation and can increase the levels of TNFα, IL-1β, IL-6, and IL-18 within adipose tissue and systemically, such as through inflammasome activation in macrophages." (PMID 37526777, 2023). "This outcome is also in line with the evidence in obesity studies that showed increased expression of IL-6 correlates with the increase in fat mass." (PMID 37629569, 2023). "This was in accordance with previous findings showing that IL-6 plays a significant role in lipid metabolism by preventing obesity development." (PMID 36834025, 2023). "The PERK pathway during excessive ER stress also activates cytokines such as TNF-a, IL-6, and IL-1β, a major contributor to the inflammation that induces obesity." (PMID 38140341, 2023). "Nevertheless, one study reported that 1000 mg of vitamin C supplementation for 8 weeks significantly reduced CRP and IL‐6 levels in participants with obesity, hypertension, and/or diabetes." (PMID 37823170, 2023). "Obesity creates a proinflammatory environment characterized by high levels of circulating interleukin-6, tumor necrosis factor-α, C-reactive protein, and a relative deficiency of protective immune cell types." (PMID 37901321, 2023). "Low-grade obesity-induced inflammation leads to the generation of IL-6 and TNF-α with tumor-promoting effects, activating tumor-associated neutrophils and macrophages." (PMID 37834153, 2023). "Both IL-6 and CRP levels were associated with the obesity characterized by an increase infat mass in normal weight participants." (PMID 37242271, 2023). "Inflammation of adipose tissue and high production of TNF-α, IL-6, and IL-1β in obesity is vital for T2DM incidence and progression." (PMID 35620114, 2022). "CRP is effectively elicited by IL‐6, which is often increased in obesity, thus explaining the lower ratio found in patients with obesity." (PMID 35837843, 2022). "Adipose tissue expression of pro-inflammatory cytokines such as TNF and IL-6 promotes obesity-related insulin resistance in humans and the secretion of these molecules is often increased with aging." (PMID 36499366, 2022). "Due to obesity and secretion of selected cytokines (IL-6 and TNF- α), the anti-inflammatory phenotype of macrophages changes into a proinflammatory phenotype." (PMID 36555323, 2022). "On the other hand, inflammatory biomarkers hsCRP, IL-6, and TNF-alpha are associated with obesity and other diseases, including inflammation, infection, heart attack risk, and cancer." (PMID 35053667, 2022).
Obesity (continued). "Increases in serum IL-6, TNF-α, MCP-1, and TBARS, and reduction in serum TAC was statistically associated with the history of dyslipidemia, diabetes, and obesity." (PMID 36032093, 2022). "Conversely, mice with the myeloid cell-specific deletion of IL-6Rα show enhanced systemic inflammation and glucose intolerance 378), suggesting that IL-6 plays an unexpected role in limiting inflammation in obesity." (PMID 35909571, 2022). "In summary, perinatal HFD with maternal obesity induces early postnatal obesity with transiently elevated adipocytokine levels of IL-6 and leptin along with impaired glucose metabolism in the offspring." (PMID 35896539, 2022). "Evidence from a longitudinal study indicates that children with higher plasma IL6 levels are related to obesity, metabolic syndrome, and greater asthma severity, with a risk for asthma exacerbation and decreased lung function." (PMID 36140412, 2022). "A total of 24 osteoporosis-related genes, including IGF1, IL6, pyruvate dehydrogenase kinase 4 (PDK4), PPARGC1A, and TF, were also associated with obesity and diabetes." (PMID 35328013, 2022). "The accumulation of macrophages in adipose tissue can result in the secretion of proinflammatory cytokines, such as interleukin 6 (IL-6), and leads to inflammatory response and obesity-induced insulin resistance in adipose tissue." (PMID 35807667, 2022). "One possibility is the consistent reduction in the obesity proinflammatory state indicated by lower levels of C reactive protein and interleukin-6 (IL-6) after bariatric surgery." (PMID 36033567, 2022). "Logistic analysis revealed that after adjusting for sex, age, hypertension, obesity, as well as IL-10, IL-4, and IL-6, an increased plasma level of TNF-α was significantly associated with sarcopenia (P < 0.001)." (PMID 36160136, 2022). "Obesity, which is closely associated to T2DM, leads to high proinflammatory cytokines (IL1, IL6, IL8, TNF-alpha) and adipokines which further hinder the subjects’ immunity." (PMID 36360537, 2022). "In patients with obesity and diabetes, fasting glucose, the HOMA index, HbA1c and IL-6 were significantly higher than in participants in the obesity group and control group." (PMID 35585213, 2022). "Obesity, as a chronic inflammatory condition, has been well reported to maintain increased systemic interleukin (IL)-2, IL-4, IL-6, TNFα, IFNγ, and GM-CSF levels in a manner modulated by physical activity." (PMID 36143948, 2022). "Thus, obesity may cause kidney damage by promoting the production of IL-6 and TNF-α." (PMID 35054932, 2022). "The state of inflammation in obesity is associated with adipose tissue dysfunction, which increases the secretion of pro-inflammatory cytokines such as TNF-α, CRP, and IL-6." (PMID 35740977, 2022). "Obesity and inflammatory markers such as tumor necrosis factor-α and interleukin-6 were considered in relation to TyG; these factors can increase the difficulty of surgery and the possibility of blood transfusion." (PMID 35480095, 2022). "Among them, IL-6 is suggested to play an essential role in the treatment of obesity and inflammation by acupuncture, and IL-6 was significant in both Boxplot and Survival Analysis of pancreatic cancer (PAAD)." (PMID 36105933, 2022). "In the same study, B cells from PBMC of subjects with obesity produced less IL-6 upon ex vivo stimulation despite having elevated proportions of total B cells compared to lean subjects." (PMID 35252310, 2022). "Current studies have confirmed that obesity is related to inflammation and that levels of the proinflammatory cytokines IL-6 and TNF-α increase in individuals with obesity." (PMID 35341146, 2022). "Obesity itself promotes inflammation by increasing pro-inflammatory cytokines such as interleukin-6 and necrosis factor-alpha." (PMID 36292469, 2022). "Obesity is also related to increases in pro-inflammatory cytokines, such as interleukin-6 (IL-6) and tumor necrosis factor-alpha (TNF-α)." (PMID 35571885, 2022).
Obesity (continued). "IL-6 is directly related to BMI by acting on adipocytes and is increased in individuals with insulin resistance, obesity, and T2DM." (PMID 36362238, 2022). "Inflammation and adipocyte-derived factors including TNF-α and IL-6 have been reported to link obesity to T2DM." (PMID 36012215, 2022). "This fact is due to the proinflammatory state of obesity, since the increased levels of IL-6 and TNF-α reduce the expression of PPAR-γ-2 and C/EBPα, which play an important role in the correct differentiation of preadipocytes into adipocytes." (PMID 35955431, 2022). "IL‐6 is usually elevated in obesity, with the adipose tissue being a major contributor to its circulating levels, as adipocytes and immune cells of the adipose tissue are important sources." (PMID 35837843, 2022). "Individuals living with obesity in the current study exhibited higher circulating concentrations of IL-6 and higher HOMA2-IR scores in conjunction with downregulation of scWAT WNT5A mRNA expression." (PMID 35958557, 2022). "IL-6 also stimulated glycerol secretion of subcutaneous and omental AT cultures isolated from human donors with obesity in vitro, suggesting IL-6 stimulates basal lipolysis in adipocytes." (PMID 35557517, 2022). "In both human and animal models, diet-induced obesity is associated with increased circulating inflammatory markers such as TNF-α, IL-1β, and IL-6, which represent a key step in the development of insulin resistance in peripheral organs." (PMID 35871167, 2022). "This adipokine in adipose tissue activates insulin insensitivity and obesity via the enhancement of the level of interleukin 6 (IL-6)." (PMID 35178210, 2022). "Together, these data suggest that IL-6 released due to exercise overlaps with the anorexigenic effect of leptin in the context of diet-induced obesity." (PMID 36452038, 2022). "Obesity is linked to elevated levels of inflammatory serum markers such as C-reactive protein (CRP), interleukin-6 (IL-6), and tumor necrosis factor alpha (TNFa)." (PMID 35679338, 2022). "As expected, IL-1 and IL-6 were increasing parallel to the severity of DM and/or obesity in the experimental animals." (PMID 36405233, 2022). "The overexpression of IL-6 in high-fat diet-induced obese mice reduced their body weight and improved their obesity-induced fatty liver and insulin resistance." (PMID 36408139, 2022). "The IL-6 contributes to inflammation in all insulin target tissues, including fat, the liver, and muscle, indicating the role of IL-6 in driving obesity and in the pathogenesis of systemic insulin resistance." (PMID 35846757, 2022). "Pro-inflammatory cytokines such as IL-1β, IL-6, and TNF-α closely interact with immune and metabolism regulatory systems and modulate the risk for diabetes mellitus type II and obesity." (PMID 35206947, 2022). "First, maternal obesity-induced early transient obesity with an increase in serum IL-6 concentration and metabolic disorders in offspring." (PMID 35896539, 2022). "Taken together, these data reveal an essential role for Phillyrin in restoring IL-6-linked excessive basal lipolysis and indicate a potential for targeting IL-6/ATGL signaling to combat metabolically unhealthy obesity." (PMID 36276810, 2022). "Recent studies have supported the use of the IL‐6R inhibitor tocilizumab, and the use of colchicine in COVID‐1947 was associated with the reduction of multiple inflammatory mediators, including CRP, IL‐6, resistin, and vascular proteins in obesity." (PMID 35837843, 2022). "Supplementation with WTE prevented the obesity-induced changes in the gene expression of IL-1β, IL-6 and NOX-4 (p < 0.05 for all)." (PMID 36009292, 2022). "Among them, GSEA analysis showed that LINC01615 is associated with most of the immune pathways, such as the IL6 signaling pathway, IL1 and megakaryocytes in obesity, and the biocarta IL10 pathway." (PMID 35794984, 2022).
Obesity (continued). "Muscle atrophy is caused by proinflammatory cytokines such as tumor necrosis factor-α (TNF-α) and interleukin-6 (IL-6) secreted from fat cells enlarged by obesity." (PMID 35711555, 2022). "Researchers indicated that obesity should play a vital role in the increased secretion of cytokines such as IL-1, IL-6, IL-8, TNF-α, and CRP, and further lead to chronic low-grade inflammation." (PMID 36613000, 2022). "Specifically, Kyn stimulates AhR expression to activate the AhR/Stat3/IL-6 signaling in adipocytes, by which it mediates a systemic effect on the development of obesity and insulin resistance." (PMID 35715443, 2022). "Diets predominant in plant foods decrease obesity-related inflammatory markers, such as CRP and IL-6, which are associated with disease." (PMID 36296997, 2022). "In obesity, adipose tissue produces cytokines such as interleukin (specifically IL1ß and IL6), interferon γ (IFNγ), Tumor Necrosis Factor α (TNFα), and Monocyte Chemoattractant Protein 1 (MCP1), which promote chronic inflammation." (PMID 36009143, 2022). "Proinflammatory state existing in subjects with obesity and blood concentrations of the inflammatory markers, including C-reactive protein, interleukin-6, adipokines, fibrinogen, and PAI-1, are shown to be reduced following bariatric surgery." (PMID 35855391, 2022). "High level of interleukin 6 (IL-6), released by adipocytes in an obesity-induced, low grade inflammation state, is a regulator of insulin resistance and glucose tolerance." (PMID 36387898, 2022). "Other mechanisms are involved in obesity-derived hepatocarcinogenesis, including alterations in the signaling pathways of IL-6, PTEN, NF-κB, Hedgehog, TNF-α, and STAT3." (PMID 36612019, 2022). "Meanwhile, Phillyrin attenuates obesity-related inflammation and IL-6 production in adipose tissue in obese mice." (PMID 36276810, 2022). "Chronic low-grade inflammation, present in obesity and favored by it, causes decreased muscle anabolic function, which is mediated by variations in the production of factors such as TNF, IL-6, leptin and GH." (PMID 35326591, 2022). "Muscle atrophy is induced by inflammatory cytokines such as TNF-α and IL-6 secreted from fat cells enlarged by obesity." (PMID 35711555, 2022). "Among these, the close associated of cytokines with obesity, TNF-α, IL-6 and adiponectin are further introduced." (PMID 35054932, 2022). "As the effects of central IL-6 on food intake and glucose homeostasis are reported to be enhanced by obesity, we next examined the effect of 20 weeks HF diet on IL-6Ra KD and Cre+/- mice (12–14 weeks old)." (PMID 35470093, 2022). "It has been shown that IL-6 has an important role in obesity and insulin resistance but also is cardinal in driving the beneficial effects of physical exercise in glucose and insulin sensitivity as well as body composition." (PMID 36387898, 2022). "It is beieved that IL-6 secreted by adipocytes during obesity would promote chronic inflammation and exacerbate metabolic syndrome." (PMID 35715443, 2022). "Fasting glucose, the HOMA index, triglycerides and IL-6 rose progressively from participants in the Control to Obesity to Obesity and Diabetes cohorts." (PMID 35585213, 2022). "The potential bridging role of IL-6 between asthma and obesity has been sustained by the increasing levels of IL-6 with BMI in children, and by the correlation between IL-6 with and the probability of asthma exacerbation." (PMID 35055456, 2022). "These suggest that adipokines play an integral role in the development of obesity-induced kidney damage —for example, elevated levels of TNF-α, and IL-6 are associated with a more accelerated progression of CKD." (PMID 35054932, 2022). "Obesity is associated with chronic low-grade systemic inflammation and the secretion of proinflammatory cytokines (TNF-α, IL-6, and IL-8) by adipocytes or adipose tissue-infiltrating immune cells." (PMID 35887932, 2022).